ALK (ALK receptor tyrosine kinase)
Diseases named in the same sentence as ALK in open-access papers (continued):
Sharing a sentence is not in itself a finding about the gene and the disease.
neuroblastoma (continued). "We add to this evidence by showing that shRNA-mediated NF1 knockdown renders two oncogenic ALK-driven human neuroblastoma cell lines resistant to pharmacological ALK inhibition, and by confirming that ALK mRNA is expressed in neurofibroma-derived NF1−/− human Schwann cells." (PMID 24278035, 2013). "However, ALK is also known to be mutated in the context of the full-length receptor tyrosine kinase (RTK), this being most clearly understood in neuroblastoma." (PMID 23889739, 2013). "Interestingly, decreased cell proliferation was reported in in vitro cultured neuroblastoma cell lines where ALK has been depleted by siRNA." (PMID 23667670, 2013). "cyclin D is overexpressed in many cancers including ALK positive neuroblastomas." (PMID 23667670, 2013). "Here, we report similar basal patterns of ALK phosphorylation between the neuroblastoma IMR-32 cell line, which expresses only the wild-type receptor (ALKWT), and the SH-SY5Y cell line, which exhibits a heterozygous ALK F1174L mutation and expresses both ALKWT and ALKF1174L receptors." (PMID 22479414, 2012). "Ours results on ALK phosphorylation pattern in neuroblastoma cell line required two major comments." (PMID 22479414, 2012). "This region includes both MYCN and ALK, two well characterized oncogenes in neuroblastoma." (PMID 22788920, 2012). "The ALK RTK gene, which is translocated and fused to various partner genes in lymphomas and non-small cell lung cancer, has been found amplified and mutated in neuroblastoma." (PMID 19226453, 2009). "Nevertheless, the finding of ALK amplification in neuroblastoma may provide a novel therapeutic target that could be tested using available ALK inhibitor compounds." (PMID 17327916, 2007). "Furthermore, the utilization of circulating tumor DNA as a non-invasive approach for longitudinal monitoring of ALK-positive neuroblastoma patients, in combination with radiographic evaluation of treatment response, holds promise for understanding dynamic tumor changes over time." (PMID 40064818, 2025). "This is supported by the patient TMA IHC data demonstrating significant ALK protein expression across a diverse group of neuroblastoma tumors, suggesting that the vast majority of patients are above the therapeutic threshold of ALK surface expression and could benefit from an ALK-directed ADC." (PMID 40813394, 2025). "Mutations in the RAS pathway occur frequently in neuroblastoma, not only in the RAS gene itself, but also through mutations in regulatory proteins and downstream signaling components (e.g., NF1 and PTPN11) or by triggering constitutive activation of the receptor kinases of the pathway (e.g., ALK)." (PMID 40115016, 2025). "Importantly, ALK protein expression in neuroblastomas correlates with a poorer prognosis." (PMID 38339401, 2024). "The poor prognostic risk factors of locoregional neuroblastoma (LR-NB) include age, MYCN or MDM2-CDK4 amplification, 11q, histology, diploidy with ALK or TERT mutations, and ATRX aberrations." (PMID 38730688, 2024). "In addition, while human neuroblastoma cell lines can contain both mutant/amplified ALK and amplified MYCN, these tumor-derived lines also have other mutations that likely impact effects of ALK and MYCN." (PMID 38451815, 2024). "This sheds light on potential therapeutic avenues, suggesting that targeting ALK with kinase inhibitors or specific antibodies could hold promise in neuroblastoma treatment, especially considering the possibility of these antibodies inducing receptor internalization and downregulation." (PMID 38397899, 2024). "Here, we present a comprehensive NB-ALK sequencing panel that enables longitudinal ctDNA analysis in patients with ALK-driven relapsed or refractory neuroblastoma." (PMID 39177282, 2024). "On the flip side, although cleaving ALK’s intracellular domain may help ALK-targeted therapy, cleavage of its extracellular side fosters ALK-related tumor formation and the movement of cells in neuroblastoma." (PMID 38397899, 2024).
neuroblastoma (continued). "Thus, ALK drives neuroblastoma in part through a feedforward loop between POSTN and WNT signaling." (PMID 38451815, 2024). "We identified SLC3A2 as a potential Anaplastic Lymphoma Kinase (ALK) interacting partner in a BioID-proximity labeling screen in neuroblastoma (NB) cells." (PMID 38858548, 2024). "The same synergy is found between MYC-driven neuroblastoma and Augα overexpression, suggesting that inhibitory antibodies might be effective for patient subgroups with ligand misregulation in addition to the potential benefits of ALK TKI treatment." (PMID 37892172, 2023). "Moreover, ALK rearrangements have been identified in ALCL (translocation, 60%), thyroid cancer (translocation, 2.2%), and neuroblastoma (point mutation, 10.5%), among others." (PMID 37954850, 2023). "Finally, universal cytoplasmic ALK expression is also widely observed in neuroblastomas, suggesting that some transcriptional or posttranslational regulation of the ALK might exist in these tumor cells." (PMID 37592266, 2023). "Outcome of neuroblastoma patients did not significantly depend on the type of ALK mutations, although OS of patients with F1174L mutations tended to be slightly worse than that of patients with tumors harboring other ALK mutations or ALK wildtype tumors." (PMID 36807339, 2023). "In children, adolescents and adults with mutated ALK-driven relapsed or refractory neuroblastoma, a third-generation ALK inhibitor with or without chemotherapy was well tolerated, and recommended phase 2 doses were successfully identified in all patient groups." (PMID 37012551, 2023). "Clearly, the peptide described here requires development to improve its pharmacodynamics and pharmacokinetics properties further, but it may represent a promising therapeutic tool for the treatment of aggressive neuroblastoma resistant to current ALK inhibitors." (PMID 37765276, 2023). "The selective differences in TNO155 sensitivity that we observed between ALK mutated and nonmutated neuroblastoma cells resemble those reported for ALK-TKI treatments; however, our results reveal no substantial differences based on specific ALK missense mutations." (PMID 38032104, 2023). "Because of the trial set-up, the exact type of ALK alteration was not always reported so it is unknown if there were specific ALK point mutations in neuroblastoma that were resistant to ceritinib." (PMID 37773318, 2023). "Our results report the first evaluation of TNO155 in neuroblastoma and suggest that combinatorial inhibition of ALK and SHP2 could be a novel approach to treating ALK-driven neuroblastoma, potentially including the increasingly common tumors that have developed resistance to ALK-TKIs." (PMID 38032104, 2023). "Together, the chronology of the occurrence of mutations in this tumor indicates that ALK F1174L mutations may not necessarily prevail in neuroblastoma, both in the absence and presence of a concurrent ALK R1275Q mutation." (PMID 36807339, 2023). "By studying the association of mutational variants of candidate neuroblastoma genes with clinical, cytogenetic and pathological characteristics, and survival outcomes, we found 1p candidate genes CHD5 and KIF1Bβ to be most frequently mutated after ALK, ATRX, and BARD1." (PMID 35768791, 2022). "Importantly, potent ALK inhibitors are already in clinical trials for ALK-mutant neuroblastomas." (PMID 34716856, 2022). "Only few mechanisms of ALK inhibitor resistance have been detected in preclinical models of neuroblastoma so far, most of which were adaptive epigenetic or gene expression changes that have not yet been observed in patients developing resistance and may not be therapeutically actionable." (PMID 35689207, 2022). "Moreover, we identified hypersensitivity to MEK inhibition as a novel collateral sensitivity specific to NF1 loss, which may represent a clinically actionable therapeutic strategy for ALK-inhibitor resistant neuroblastoma." (PMID 35689207, 2022).
neuroblastoma (continued). "Our study is consistent with ALK mutations in neuroblastoma being branch‐type rather than truncal and may not confer a survival advantage." (PMID 36029175, 2022). "Since many neuroblastomas express ALK, our results suggest that some “ALK mutation‐negative” NB may respond to ALK TKI treatment." (PMID 33411331, 2021). "Moreover, by whole exome sequencing, we demonstrated that NB exo-DNA represents the entire exome and that it carries tumor-specific genetic mutations, including those occurring on known oncogenes and tumor suppressor genes in neuroblastoma (ALK, CHD5, SHANK2, PHOX2B, TERT, FGFR1, and BRAF)." (PMID 33915956, 2021). "ALK mutations have been associated with poorer survival in high-risk neuroblastoma, and ALK gene is amplified in a subgroup of MYCN-amplified neuroblastoma tumors due to the proximity of the two loci (2p23-24) at the 2p-gain region associated with high-risk neuroblastoma." (PMID 34957126, 2021). "Indeed, such events in 11q-deletion can be further impacted on by deregulated oncogenic activities, such as MYCN amplification and aberrant ALK/MAPK signaling, resulting in normal cell development veering off-track and promoting evolution of high-risk neuroblastoma." (PMID 34885007, 2021). "Furthermore, the authors could correctly identify MYCN and ALK amplification or diploid status in plasma samples from mice with established neuroblastoma xenografts and from patients at diagnosis, in accordance with FISH results on the primary tumor." (PMID 34680298, 2021). "Here, evaluation of ALKAL2 levels in neuroblastoma could provide a potential biomarker for ALK signaling activity that is not captured by genetic mutation analysis." (PMID 34885007, 2021). "The response to crizotinib or other ALK inhibitors is presently unknown, but preclinical studies have shown that R1275Q cell lines are sensitive to crizotinib, and clinical trials investigating crizotinib in neuroblastoma are underway." (PMID 32441866, 2020). "In addition to ALCL, ALK auto-antibodies have been detected in ALK-positive NSCLC patients (62%; 13/21 cases), in lymphoma patients with ALK-translocation unrelated to NPM-ALK (59%; 13/22 cases), in one ALK-positive rhabdomyosarcoma patient, as well as in an ALK-WT neuroblastoma patient." (PMID 32059449, 2020). "This suggests that this mutagenic process, which is caused by ROS in other settings (though not proven in neuroblastoma), may promote evolution and heterogeneity, as many driver SNVs, such as ALK mutations, are later events in neuroblastoma." (PMID 33056981, 2020). "Additionally, a newer target for neuroblastoma treatment is anaplastic lymphoma kinase (ALK)." (PMID 31847387, 2019). "No distinct mutation spectrum in relation to neuroblastoma tumours genomic subtypes could be detected although there was a paucity of ALK mutations among 11q-deleted tumors." (PMID 30778092, 2019). "However, its success in neuroblastoma patients is yet not fully evaluated, apart from a favorable case report for a tumor harboring an ALK I1171T mutation." (PMID 35582571, 2019). "In neuroblastoma, the picture of acquired resistance to ALK inhibitors may be very different." (PMID 35582571, 2019). "Although these trials focus on children already diagnosed with neuroblastoma, it is also conceivable that children diagnosed with a germline ALK mutation early in life could benefit from regular screening for neuroblastoma and early initiation of an ALK inhibitor may be warranted." (PMID 30200332, 2018).
neuroblastoma (continued). "Furthermore, high-risk neuroblastoma can be classified into different biological subsets based on molecular characterization including MYCN amplification status, c-MYC expression, ALK and ATRX mutations, TERT rearrangements and alternative mechanisms of telomere lengthening (ALT)." (PMID 28924803, 2018). "The anaplastic lymphoma kinase (ALK) gene was identified as a neuroblastoma predisposition gene in 2008 in two studies; one, a genetic linkage study across 20 families with neuroblastoma and the other, a genome-wide comparative genomic hybridization analysis of 592 neuroblastoma tumors." (PMID 30200332, 2018). "Additionally, 15–20% of neuroblastoma patients overexpress wild type ALK in the absence of an activating mutation." (PMID 30459759, 2018). "Moreover, deregulation of ALK has been reported in neural cancers such as neuroblastoma, which signifies that ALK might also have complementary interactions with other neurotrophic factors to regulate processes important for cancer cell survival." (PMID 28557340, 2017). "While it is possible that some of the other candidate mutations may be activating in nature they have not been tested and none overlap with mutations shown to activate ALK in neuroblastoma." (PMID 28030793, 2017). "Additionally, we recently demonstrated an unexpected role for the leucine G-protein coupled receptor (LGR5) as a critical upstream regulator of MEK-ERK signaling and cell survival of different neuroblastoma genetic subtypes, including ALK and NRAS mutant lines." (PMID 28602975, 2017). "Here we investigate the recently described ALK inhibitor PF-06463922 (lorlatinib) in neuroblastoma driven by expression of wild-type or mutant ALK, with a focus on whether PF-06463922 is more effective than crizotinib against those mutants known to confer crizotinib resistance." (PMID 27483357, 2016). "While some of these mutations have been observed previously in the context of ALK-fusion cancers, we characterize two novel mutations that thus far have only been observed in neuroblastoma – T1151M and R1192P – and two mutations not previously characterized in ALK+ ALCL." (PMID 27009859, 2016). "Although ∼7% of neuroblastoma is ALK-positive at diagnosis, recent data indicate that the incidence of ALK mutations may be 20-25% in patients with relapsed neuroblastoma, regardless of initial ALK status." (PMID 27483357, 2016). "Therefore, excessive JNK activity could be exploited as a potential biomarker of ALK inhibitor sensitivity in neuroblastoma." (PMID 27732954, 2016). "The crizotinib-resistant ALKF1174L mutation arises de novo in neuroblastoma (NB) and is acquired in ALK translocation-driven cancers, lending impetus to the development of novel anaplastic lymphoma kinase (ALK) inhibitors with different modes of action." (PMID 26616860, 2016). "However, the downstream signaling pathways affected by aberrant ALK activity in neuroblastoma remain unclear, impairing the clinical application of Crizotinib for neuroblastoma treatment." (PMID 27732954, 2016). "The most common genetic features of neuroblastoma are amplification of the proto-oncogene MYCN, deletions of parts of chromosome arms 1p and 11q, gain of parts of 17q and triploidy, and mutations in the kinase domain of ALK which occur in both sporadic and familial forms of neuroblastoma." (PMID 27049722, 2016). "Consequently, we could show that inhibition of ALK using TAE684 induces a significant decrease in cellular proliferation of neuroblastoma cell lines." (PMID 27655666, 2016). "However, suboptimal activity was found in ALK mutant-positive neuroblastoma." (PMID 27483357, 2016).
neuroblastoma (continued). "Similarly, two neuroblastoma lines carrying the ALK-F1174L mutation (SKN-SH, SH-SY5Y) and one ALK-negative neuroblastoma (SKN-AS) were treated with P36." (PMID 25950466, 2015). "Finally, ALK Mutations have been described in 10.4% of neuroblastoma samples but not in other pediatric tumors like RMS, Ewing sarcoma, or DSRCT and only occasionally in other solid tumors like CRC." (PMID 25083769, 2014). "The expression levels of the control genes (MYCN, MEIS1 and ALK) were, in all three cases, when compared to all healthy samples, healthy nervous system samples and healthy peripheral nervous system samples, highly and statistically significantly elevated in neuroblastoma." (PMID 20444257, 2010). "There was 100% overall survival in neuroblastoma xenograft models NB-1, NB-SD, COG-N-424x, and NGP ALK WT, and 40% overall survival in SK-N-AS after treatment with CDX0239-PBD." (PMID 40813394, 2025). "Recent investigations indicate that the combination of Loratinib and AMXT-1501 inhibits anaplastic lymphoma kinase (ALK), subsequently inhibiting SLC3A2 and thereby obstructing cell proliferation in neuroblastoma cell lines." (PMID 40040695, 2025). "The impact of BH-3 mimetics on RTKi resistance in neuroblastoma remains unexplored, but BH-3 mimetics enhanced MET inhibition by crizotinib in glioblastoma PDX and ALK inhibition by lorlatinib in NSCLC xenografts." (PMID 41511287, 2025). "ATP-competitive ALK/Met/ROS1 tyrosine kinase inhibitors (TKIs), such as crizotinib, exhibit differential activity in preclinical models of ALK-driven neuroblastoma." (PMID 40115016, 2025). "Treatment of neuroblastoma xenograft models with CDX0239-PBD led to maintained complete response in NB-1, NB-SD, COG-N-424x, and NGP ALK WT, and a partial response with subsequent tumor growth progression in SK-N-AS." (PMID 40813394, 2025). "We leveraged this model to uncover mechanisms by which ALK and MYCN cooperate in the pathogenesis of neuroblastoma." (PMID 38451815, 2024). "Protein abundance of KCNH1 was comparable to targets under development in neuroblastoma including NCAM1, L1CAM and CD276, and higher than other known immunotherapeutic targets such as ALK and GPC2." (PMID 38895237, 2024). "In particular, on combined treatment of neuroblastoma patient derived xenografts with an FTI and an ALK TKI complete regression of tumour growth is observed although tumours rapidly regrow on cessation of therapy." (PMID 38653965, 2024). "Several other cancers that commonly have an aberrant ALK driven growth drive are large cell neuroendocrine lung cancer (LCNEC), glioblastoma, neuroblastoma, anaplastic large cell lymphoma, and anaplastic thyroid carcinoma." (PMID 39056757, 2024). "In contrast, ALK.CAR‐Ts and GD2.CAR‐Ts were less potent against neuroblastoma tumours with lower ALK or GD2 expression, confirming the importance of antigen density for CAR‐T‐cell efficacy." (PMID 38877641, 2024). "Among the many transcription factors involved at different neuroblastoma differentiation stages, PHOX2B and MYCN with their transcriptional targets ALK and LIN28B, and the tumor suppressor miRNAs let-7, miR-34, and miR-204 are mainly involved." (PMID 38666930, 2024). "In humans, the Aanaplastic Lymphoma inase (ALK) RTK is expressed in the central and peripheral nervous system and its role as an oncogene in the childhood cancer neuroblastoma, which arises from the peripheral nervous system, is well described." (PMID 38904987, 2024). "Targeting anaplastic lymphoma kinase (ALK) has emerged as one of the most promising and specific approaches for neuroblastoma therapy." (PMID 38877641, 2024). "Nonetheless, a recent study demonstrated that many neuroblastoma (NB) cell lines exhibit IGF-1R activity, and inhibiting IGF-1R leads to decreased cell proliferation in ALK-driven NB cells." (PMID 38397899, 2024).